Y_RNA (Y RNA )
Gene: Miscellaneous RNA gene on chromosome 6 (25,287,432 to 25,287,533, reverse strand). Ensembl gene ENSG00000207286.
Homologues: Orthologues: chimpanzee Y_RNA (99% identical), macaque Y_RNA (97% identical). Paralogues in human: Y_RNA (87% identical), Y_RNA (86% identical), RNY3 (85% identical), Y_RNA (85% identical), RNY3P1 (84% identical), Y_RNA (84% identical), Y_RNA (83% identical), Y_RNA (82% identical), RNY3P11 (81% identical), Y_RNA (81% identical), RNY3P14 (80% identical), RNY3P7 (80% identical), and 94 more.